HLA-DQB1 (major histocompatibility complex, class II, DQ beta 1)
Diseases named in the same sentence as HLA-DQB1 in open-access papers (continued):
Sharing a sentence is not in itself a finding about the gene and the disease.
endometriosis (3 papers, 2020 to 2025). The growth of functional endometrial tissue in anatomic sites outside the uterine body. "In a recent study, PCR-restriction fragment length polymorphism analysis revealed that the HLA-DRB1*14:03 and HLA-DQB1*03:01 alleles are associated with endometriosis in Japanese women." (PMID 32184413, 2020). "From the results of this study, it remained unclear exactly how and to what extent PPARA and HLA-DQB1 contributed to the presence and severity of endometriosis." (PMID 39796277, 2025). "The etiological link between HLA-DQB1 and endometriosis was found at the DNA level." (PMID 39796277, 2025).
glioma (3 papers, 2015 to 2024). A benign or malignant brain and spinal cord tumor that arises from glial cells (astrocytes, oligodendrocytes, ependymal cells). "The genes analyzed included HLA‐DQA1, HLA‐DQB1, HLA‐DMB, LY86, MS4A7, FOLR2, and MS4A4A in glioma patients." (PMID 38997808, 2024).
Hypertension (3 papers, 2016 to 2022). The presence of chronic increased pressure in the systemic arterial system. "An allele of HLA-DQB1 (which encodes a class II molecule expressed in antigen-presenting cells) increases the production of autoantibodies against angiotensin AT1 receptors, which was associated with essential hypertension in Chinese patients." (PMID 32854392, 2020).
preeclampsia (3 papers, 2017 to 2023). Preeclampsia is a hypertensive disorder of pregnancy that is characterized by new-onset hypertension with proteinuria presenting after 20 weeks of gestation, and depending on mild or severe forms may initially present with severe headache, visual disturbances, and hyperreflexia. "High HLA-C, HLA-DQB1 and HLA-B eplet compatibility between mother and child is associated with severe manifestation of preeclampsia." (PMID 38022600, 2023). "In this study, the frequencies of HLA gene polymorphisms, HLA-DQA1*0102, and HLA-DQB1*0602 were investigated among healthy subjects and patients with preeclampsia." (PMID 29662965, 2017). "Given the association of HLADQB1 and KIR in preeclampsia and infectious disease which may impact infant birth and survival, they may be the actual targets of positive selection, resulting in the signatures of selection which have been seen in these loci." (PMID 32272904, 2020).
scleroderma (3 papers, 2012 to 2021). Scleroderma is a rare autoimmune connective tissue disorder characterized by abnormal hardening of the skin and, sometimes, other organs. "HLA-DQB1 has the strongest genetic association with scleroderma because of excessive fibrosis of the internal organs." (PMID 35111164, 2021). "A strong relationship between HLA haplotypes and specific scleroderma-related autoantibodies is also confirmed, with ACA being associated with HLA class II genes, namely HLA-DQB1 and HLA-DRB1." (PMID 31431952, 2018).
Sepsis (3 papers, 2018 to 2021). Sepsis is defined as life-threatening organ dysfunction caused by a dysregulated host response to infection. "In contrast to the investigated HLA-DR genes, no significant sepsis-induced changes were detected in transcription of HLA-DQA1 and HLA-DQB1 (p = 0.81 and p>0.99)." (PMID 30212590, 2018).
viral infection (3 papers, 2016 to 2024). "Furthermore, both the upregulation (KIR2DL5A/B) and downregulation (HLADQA1 and HLADQB1) of genes associated with antigen presentation suggest a heightened immune response, potentially reflecting persistent immune activation following viral infection." (PMID 39435656, 2024). "FDR analysis using all p-values obtained a minimum q-value of 27% for the associations with the four lowest p-values, namely HLA-DQB1 with sepsis infection, HLA-DQA1 with other infections, HLA-DPB1 with CNS infection and HLA-DQB1 and viral infection." (PMID 34059071, 2021).
allergic rhinitis (2 papers, 2016 to 2024). Inflammation of the nasal mucous membranes caused by an IgE-mediated response to external allergens. "Similarly, while HLA-DQB1 gene polymorphisms could indicate a relationship with allergic rhinitis, our data do not confirm a clinically significant connection." (PMID 39062002, 2024).
bipolar affective disorders (2 papers, 2021 to 2025). "A recent GWAS demonstrated that the genetic diversity of HLA-DRB1 and HLA-DQB1 alleles modulates responses to treatment with lithium-containing drugs in bipolar affective disorders." (PMID 41155473, 2025).
chronic hepatitis B (2 papers, 2018 to 2022). "However, HLA-DQB1*03:03 is associated with both an increased and decreased risk of chronic hepatitis B." (PMID 35769989, 2022). "The HLA-DQB1*06:09 and HLA-DPA1/DPB1 alleles which we reported here, have been detected to be associated with chronic hepatitis B with similar tendencies in previous reports in different ethnic groups." (PMID 35769989, 2022). "Moreover, a previous meta-analysis has indicated that some HLA-DQB1 polymorphisms (HLA-DQB1*02:01, HLA-DQB1*03:01, and HLA-DQB1*05:02) are associated with susceptibility to chronic hepatitis B (CHB), while decreased susceptibility to CHB was observed for HLA-DQB1*03:03 and HLA-DQB1*06:04." (PMID 30563535, 2018).
cutaneous melanoma (2 papers, 2020 to 2025). A primary melanoma arising from atypical melanocytes in the skin. "The Expressions of HLA Class II (HLA-DQB1) genes were Upregulated in Cutaneous Melanoma." (PMID 41574107, 2025). "In addition, compared with the normal control, the expression of IGHV1-18, CXCL11 and HLA-DQB1 were higher in the patients with cutaneous melanoma, while the expression of LTF was lower." (PMID 33585219, 2020). "We found that the expression of CXCL11 (P = 0.1), LTF (P = 0.28), and HLA-DQB1 (P = 0.67) had no significant relation to the subtypes of cutaneous melanoma through TISIDB database." (PMID 33585219, 2020).
esophageal squamous cell carcinoma (2 papers, 2015 to 2020). Esophageal squamous cell carcinoma (ESCC) is a type of esophageal carcinoma (EC) that can affect any part of the esophagus, but is usually located in the upper or middle third. "Upregulation of HLA-DQB1 has previously been reported in human esophageal squamous cell carcinoma and in canine mammary tumor." (PMID 26042423, 2015).
Hepatic fibrosis (2 papers, 2021 to 2024). The presence of excessive fibrous connective tissue in the liver. "The rs9399136 (HBS1L) is a protective variant, and rs9274407 (HLA-DQB1) is a risk variant, both contributing to liver fibrosis development." (PMID 39578894, 2024). "The studies not only revealed the protective role of rs9399136 (HBS1L) and the risk effect of rs9274407 (HLA-DQB1) toward liver fibrosis in a Taiwanese population, but also demonstrated that individual consumption patterns, such as tea uptake, have a minor impact on liver fibrosis prevention." (PMID 39578894, 2024).
hepatitis C infection (2 papers, 2011 to 2016). "The progression-related sub-network deregulated in hepatitis C infection stage was constructed with four nodes (HLA-DQA1, HLA-DQB1, HLA-DPA1 and CD74) and interactions among them." (PMID 21526182, 2011).
IgA nephropathy (2 papers, 2012 to 2015). "The intergenic region between HLA-DQB1 and HLA-DQB2 was linked to IgA nephropathy in one GWAS study; but to date no epidemiologic study has linked IgA nephropathy to kidney malignancy." (PMID 25784652, 2015).
liver diseases (2 papers, 2018 to 2019). "HLA-DQ proteins, a group of heterodimeric molecules consisted of alpha- and beta-chains encoded by HLA-DQA1 and HLA-DQB1 genes, were implicated in immune-mediated diseases, including liver diseases and cancer." (PMID 29416599, 2018). "Human HLA-DQB1 belongs to the HLA class II beta chain paralogs that are expressed in APCs and plays a central role in the immune system by presenting peptides derived from extracellular proteins, which has been recommended for the diagnosis and prognosis of HBV-associated liver diseases." (PMID 30925583, 2019).
lupus nephritis (2 papers, 2006 to 2022). Glomerulonephritis in the context of systemic lupus erythematosus. "The aim of this study was to investigate, for the first time, the association of HLA-DRB1 and HLA-DQB1 genes among Jordanian patients diagnosed with SLE and Lupus Nephritis (LN) using the Polymerase Chain Reaction-Sequence-Specific Primer (PCR-SSP) technique." (PMID 36556176, 2022). "Similarly, the absence of an association of HLA-DRB1, HLA-DQB1, and HLA-DQA1 alleles with renal involvement in our cohort may represent a power issue for HLA-DRB1*15 (HLA-DR2) and other alleles previously reported to be associated with lupus nephritis." (PMID 17076550, 2006).
malaria (2 papers, 2012 to 2018). Malaria is a serious and sometimes fatal disease caused by a parasite that commonly infects a certain type of mosquito which feeds on humans. "HLA-DRB1*01 was also negatively associated with repetitive regions of P. vivax MSP-9 antigen in the Brazilian Amazon, and HLA-DQB1*05 along with HLA-DRB1*13 has been associated with a reduced susceptibility to severe malaria in Gambian children." (PMID 29754588, 2018). "The effects of different HLA-DRB1 and HLA-DQB1 allelic groups and time of residence (years) in malaria endemic areas on the level of antibodies to PvMSP-1, PvMSP-3α and PvMSP-9, were also analyzed." (PMID 22649493, 2012).
male infertility (2 papers, 2016 to 2023). The inability of the male to effect fertilization of an ovum after a specified period of unprotected intercourse. "Most SNP-populated genes related to male infertility include HLA-DQB1 (20 SNPs), HLA-DRB1 (15 SNPs), MTHFR (10 SNPs), BRCA2 (9 SNPs), ACE (8 SNPs), CFTR (6 SNPs), CDH1 (6 SNPs), SRD5A2 (6 SNPs), HLA-DQA1 (5 SNPs) and MMP9 (5 SNPs)." (PMID 29263816, 2016).
nephrotic syndrome (2 papers, 2021 to 2025). A collection of symptoms that include severe edema, proteinuria, and hypoalbuminemia; it is indicative of renal dysfunction. "Both HLA-DQA1 and HLA-DQB1 have been linked to steroid-sensitive nephrotic syndrome, and our observed association might provide a missing link between the HLA locus and this syndrome." (PMID 34822396, 2021).
optic neuritis (2 papers, 2012 to 2025). Optic neuritis is inflammation of the optic nerve, the nerve that carries the visual signal from the eye to the brain.The conditionmay cause sudden, reduced vision in the affected eye(s). "The PLP-induced EAE in HLA-DQB1*0602 transgenic mice showed a typical caudo-rostral clinical progression that was associated with CNS demyelination, axonal damage and with optic neuritis." (PMID 22316121, 2012). "The analysis showed that a significant link between optic neuritis in MS patients and HLA-DRB1 * 15:01 and HLA-DQB1 * 06:01 alleles compared to MS group without optic neuritis." (PMID 39999097, 2025). "In addition, a significant linkage between HLA-DRB1 * 15:01 and HLA-DQB1 * 06:01 alleles (Pc ≤ 0.001 and Pc = 0.012, respectively) were presented among Jordanian MS patients with optic neuritis compared to Jordanian MS patients without optic neuritis." (PMID 39999097, 2025).
oral cancer (2 papers, 2021 to 2023). "Specifically, for oral cancer, previous GWAS identified three loci in the HLA region, including rs3828805 (chromosome 6 position 32636120) and rs3135001 (6:32670136) in HLA-DQB1 (6p21.32) and rs1265081 (6:31111675) in CCHCR1 (6p21.33)." (PMID 36769103, 2023).
Parkinson disease (2 papers, 2022 to 2023). A progressive degenerative disorder of the central nervous system characterized by loss of dopamine producing neurons in the substantia nigra and the presence of Lewy bodies in the substantia nigra and locus coeruleus. "These genes, in combination with PLEKHM1 and HLA-DQB1 are also associated with the GWAS Catalog trait, “Parkinson’s disease” (level 0)." (PMID 37336921, 2023).
pemphigus (2 papers, 2022 to 2024). Pemphigus is a group of rare autoimmune diseases that cause blistering of the skin and mucous membranes (mouth, nose, throat, eyes, and genitals).This conditioncan occur at any age, but often strikes people in middle or older age. "Data of 15 HLA-DRB1 alleles (DRB1*01–16) and five HLA-DQB1 alleles (DQB1*02–06) could be extracted from studies on pemphigus, MuSK MG and TTP." (PMID 35654912, 2022). "Furthermore, human leukocyte antigen (HLA) molecules, including alleles HLA-DQB1*0503 and HLA-DRB1*0402 in pemphigus, as well as HLA-DQB1*0301 in pemphigoid, may represent key predisposing factors for drug-induced AIBDs." (PMID 38793716, 2024). "While we could confirm the positive association with HLA-DRB1*14, HLA-DQB1*05 and the HLA-DRB1*14-DQB1*05 haplotype after exclusion of pemphigus patients, the frequency of HLA-DRB1*04 was significantly decreased, suggesting this association is specific for pemphigus." (PMID 35654912, 2022).
periodontitis (2 papers, 2020 to 2025). An acute or chronic inflammatory process that affects the tissues that surround and support the teeth. "Frequencies of HLA-A9 and -B15, HLA-DQA1*03:01, HLA-DQB1*03:02 and HLADQB1*03:05 alleles, as well as that of the HLA-DRB1*04:01 allele, were significantly higher in patients with aggressive periodontitis compared with control subjects among Caucasians and Iranian patients." (PMID 32515416, 2020). "However, unlike other loci, such as HLA-DQA1* and HLA-DQB1*, which did not display significant associations with the severity or extent of periodontitis in the sample, this work identified an interesting pattern connected to two alleles of the HLA-DRB1 locus: HLA-DRB1*03 and HLA-DRB1*15." (PMID 40283738, 2025).
podoconiosis (2 papers, 2012 to 2024). A disease of the lymphatic vessels of the lower extremities that is caused by chronic exposure to irritant soils. "The present study and a previous one also showed that the frequencies of HLA-DQB1*02 (a risk allele for podoconiosis) and HLA-DRB1*13 (a protective allele against podoconiosis) in the Ethiopian population were among the highest in Sub-Saharan Africa." (PMID 22761960, 2012).
pulmonary fibrosis (2 papers, 2021). Chronic progressive interstitial lung disorder characterized by the replacement of the lung tissue by connective tissue, leading to progressive dyspnea, respiratory failure, or right heart failure. "Among the 226 analyzed genes, only HLA-DRB1 and HLA-DQB1 genes and their relationships with pulmonary fibrosis were previously analyzed." (PMID 33446833, 2021).
sarcopenia (2 papers, 2020 to 2023). Progressive decline in muscle mass due to aging which results in decreased functional capacity of muscles. "HLA-DQB1 is nominally associated with sarcopenia (EWGSOP combined definition)." (PMID 37653517, 2023).
sicca syndrome (2 papers, 2022 to 2025). "In Sjögren’s syndrome, HLA-DQB1 is crucial for the presentation of antigens." (PMID 40321894, 2025).
silicosis (2 papers, 2021 to 2024). Silicosis is a respiratory disease caused by breathing in (inhaling) silica dust. "The mutant A allele of rs9273410 was associated with increased silicosis susceptibility by modulating the expression of HLA-DQB1." (PMID 35111164, 2021). "However, none of these studies, including the current study, elucidated the potential epitope or the mechanism by which HLA-DQB1 contribute towards silicosis or the development of fibrosis." (PMID 38448477, 2024). "In conclusion, our study identified an eQTL-SNP rs9273410 located on HLA-DQB1 that might contribute to the development of silicosis." (PMID 35111164, 2021).
thyroid (2 papers, 2019 to 2024). "HLA-DQB1 genotypes with AITD, HT, and BGD did not reveal any significant association with thyroid pathology." (PMID 38672712, 2024).
uveitis (2 papers, 2023). An inflammatory process affecting a part of or the entire uvea. "The frequency of HLA-C*01, HLA-DRB1 *04:05, and HLA-DQB1*04:01 was significantly higher in cases with VKH-like uveitis (P = 0.029)." (PMID 37604934, 2023).
adenoma (1 paper, 2022). A neoplasm arising from the epithelium. "There are limited studies on relationship of HLA-DQB1 with adenomas or malignities." (PMID 35486660, 2022).
carpal tunnel syndrome (1 paper, 2026). Entrapment of the median nerve in the wrist that is characterized by numbness, tingling and painful movement. "These included associations with genes involved in neurotransmitter signaling (HTR3A), immune function (HLA-DQB1, BCL11A), extracellular matrix remodeling (COL11A1, ADAMTS17, LOXL4), axon guidance and neural development (DCC, ETV1, NEGR1), and carpal tunnel syndrome (DIRC3)." (PMID 41518141, 2026).
cervical disease (1 paper, 2025). "Variants at HLA‐DQB1 have previously been associated with an increased risk of cervical disease and increased HLA‐DQB1 may act as a biomarker for cervical cancer, with its expression being associated with an increased immune response to cervical tumors." (PMID 39891432, 2025).
chlamydia (1 paper, 2023). "This study included 165 chlamydia-infected African American women from a cohort whom we previously evaluated for association of specific HLA-DQB1 alleles with chlamydia reinfection at 3 and 6 month follow-up visits after treatment." (PMID 37958786, 2023).
chronic obstructive pulmonary disease (1 paper, 2021). A chronic and progressive lung disorder characterized by the loss of elasticity of the bronchial tree and the air sacs, destruction of the air sacs wall, thickening of the bronchial wall, and mucous accumulation in the bronchial tree. "Their results also revealed that HLA-DQB1 was associated with chronic obstructive pulmonary disease." (PMID 35111164, 2021).
Cirrhosis (1 paper, 2024). A chronic disorder of the liver in which liver tissue becomes scarred and is partially replaced by regenerative nodules and fibrotic tissue resulting in loss of liver function. "Moreover, we found that the variants near HKDC1, HLA-DQB1 and MAMSTR likely influence cirrhosis via pathways distinct from those related to fatty liver disease." (PMID 38632349, 2024).
complication (1 paper, 2008). Any disease or disorder that occurs during the course of, or because of, another disease, treatment, or procedure. "HLA-DQB1*0502 was also weakly associated with SJS/TEN with ocular complications although correction of the p-value for the number of alleles detected rendered the result not significant." (PMID 18385790, 2008).
Coronary arteriosclerosis (1 paper, 2024). "Coronary arteriosclerosis shared 10 GWS genes with AD (BAG6, C6orf10, HLA-DQB1, HLA-DRA, HLA-DRB1, NDUFAF6, NME7, PLCG2, PRRC2A, and TRIB1), while myocardial infarction shared three genes with AD (HLA-DRA, PHB, and RP11-81K2.1)." (PMID 39201500, 2024).
Cryptosporidium infection (1 paper, 2021). "Moreover, we previously identified associations between alleles HLA-B*15, HLA-DQB1*03:01 and haplotype HLA-DRB1*11:01/HLA-DQB1*03:01 with increased incidence of asymptomatic and symptomatic Cryptosporidium infection." (PMID 33910121, 2021).
duodenitis (1 paper, 2024). Acute or chronic inflammation of the duodenum. "Others included 41 GWS genes for GERD (Pgene-GERD < 2.62 × 10−6), 11 for PUD (Pgene-PUD < 2.62 × 10−6), three (RNF5, HLA-DQA1, and HLA-DQB1) for gastritis-duodenitis (Pgene-gastritis-duodenitis < 2.62 × 10−6), and three (HLA-C, PITPNM2, and MPHOSPH9) for IBS (Pgene-IBS < 2.62 × 10−6)." (PMID 38802514, 2024). "Additionally, we found two overlapping genes (HLA-DQA1 and HLA-DQB1) across T2D, IBD, and gastritis-duodenitis." (PMID 38802514, 2024).
gestational diabetes mellitus (1 paper, 2025). "The genetic variations in the HLA-DQA1 and HLA-DQB1 genes may collectively contribute to the susceptibility to gestational diabetes mellitus." (PMID 40771282, 2025).
hypertriglyceridemia (1 paper, 2022). A laboratory test result indicating elevated triglyceride concentration in the blood. "Thus, the relatively reduced TG concentrations among adults classified as having T2D and the HLA-DQB1 risk allele may reflect the lack of hypertriglyceridemia typically observed with more typical hyperinsulinemic T2D." (PMID 36269708, 2022).